RN7SL674P (RNA, 7SL, cytoplasmic 674, pseudogene)
Gene: Miscellaneous RNA gene on chromosome 2 (11,584,773 to 11,585,047, forward strand). Ensembl gene ENSG00000239899.
Homologues: Orthologues: chimpanzee Metazoa_SRP (93% identical), rat Metazoa_SRP (76% identical), mouse Rn7s6 (75% identical), pig Metazoa_SRP (74% identical), rabbit Metazoa_SRP (73% identical), mouse Gm23153 (73% identical), rat Metazoa_SRP (73% identical), rat Metazoa_SRP (72% identical), dog Metazoa_SRP (72% identical), dog Metazoa_SRP (70% identical), guinea pig Metazoa_SRP (65% identical), guinea pig Metazoa_SRP (63% identical), and 1 more. Paralogues in human: RN7SL1 (82% identical), RN7SL3 (81% identical), RN7SL2 (81% identical), RN7SL5P (79% identical), RN7SL128P (77% identical), RN7SL4P (77% identical), RN7SL230P (75% identical), RN7SL480P (75% identical), RN7SL49P (75% identical), RN7SL672P (75% identical), RN7SL278P (74% identical), RN7SL752P (74% identical), and 698 more.